RPN2 (ribophorin II)
Diseases named in the same sentence as RPN2 in open-access papers (continued):
Sharing a sentence is not in itself a finding about the gene and the disease.
cancer (39 papers, 2011 to 2025). A tumor composed of atypical neoplastic, often pleomorphic cells that invade other tissues. "Ribophorin II expression status is a predictive marker for drug resistance, cell proliferation, and motility in various cancers, and higher ribophorin II expression is associated with poor patient prognosis." (PMID 34512323, 2021). "RPN2 has been demonstrated to be a prognostic marker of human cancer, is highly expressed in cancer stem cells and associated with metastasis)." (PMID 30028875, 2018). "Various reports have found that RPN2 is associated with the growth of cancer cells; however, the specific development mechanisms have not been clearly elucidated." (PMID 29069815, 2017). "In this study, we demonstrate that cancer malignancy associated with the glycosylation of CD63 is regulated by RPN2." (PMID 24884960, 2014). "We also analyzed the correlation between RPN2 and cancer hallmark pathways." (PMID 36168628, 2022). "In addition to its role in N-linked glycosylation, ribophorin II is an important molecular marker in various cancers and has been associated with drug resistance in solid cancers." (PMID 34512323, 2021). "However, little is currently known regarding the association between RPN2 and specific glycosylated proteins that are related to cancer malignancy." (PMID 24884960, 2014). "However, the underlying mechanism by which RPN2 regulates cancer cell proliferation remains unclear." (PMID 29069815, 2017). "Although prior studies have highlighted the role of RPN2 in various cancers, the impact of RPN1 has been relatively understudied." (PMID 39749324, 2024). "Ribophorin II (RPN2), a part of an N-oligosaccharyl transferase complex, plays vital roles in the development of multiple cancers." (PMID 35156537, 2022). "The expression level of ribophorin II has been proposed as a predictive marker for drug resistance, cell proliferation, and motility in various cancers." (PMID 34512323, 2021). "A few studies have assessed the relationship between RPN2 expression and clinical disease outcomes; however, they were mainly conducted in gastroenterology cancers." (PMID 34575229, 2021). "Numerous studies have examined the molecular functions and clinical relevance of ribophorin II in a variety of human cancers." (PMID 34512323, 2021). "Mounting evidence indicates that RPN2 is a significant oncogene and plays a crucial role in cancer progression and drug resistance." (PMID 33087705, 2020). "In cancer cells, RPN2 was described as being involved in the regulation of proliferation and migration, and in human airway smooth muscle cells, the protein MVP was found to be involved in growth/survival signaling pathways." (PMID 32283676, 2020). "Ribophorin II (RPN2), a protein component of an N-oligosaccharyl transferase complex, has been associated with chemotherapy drug resistance in multiple cancers, including GBM." (PMID 32404045, 2020). "Ribophorin II (RPN2) is a part of an N-oligosaccharyltransferase complex, which is excessively expressed in many kinds of cancers." (PMID 30940778, 2019). "In various human malignant tumors, RPN2 silencing was correlated with reduced tumor growth and distant metastasis and increased sensitivity to chemotherapy drugs response." (PMID 29069815, 2017). "Various studies have found that silencing ribophorin II (RPN2) inhibits cell growth in several cancers." (PMID 29069815, 2017). "EGFR has been identified as a key driver of proliferation and survival signaling in malignant tumors; therefore, we sought to investigate RPN2 silencing-mediated OST impact on EGFR function." (PMID 29069815, 2017). "We also found that the expression level of RPN2 in CRC negatively correlated with the differentiation state of the cancer cells." (PMID 29069815, 2017). "In conclusion, these data suggest that RPN2 is involved in the regulation of lethal cancer phenotypes and represents a promising new target for RNAi-based medicine against NSCLC." (PMID 25595901, 2015).
cancer (continued). "In conclusion, this study suggests that RPN2 silencing contributes to the regulation of lethal cancer phenotypes and provides a recurrence and survival advantage in NSCLC." (PMID 25595901, 2015). "Our preclinical studies demonstrate the clinical relevance of RPN2-mediated cancer malignancy in various types of solid cancer." (PMID 25595901, 2015). "This study reported that silencing of RPN2 reduced the glycosylation and membrane localization of P-gp, thereby sensitizing cancer cells to docetaxel." (PMID 25789057, 2015). "Specifically, silencing of RPN2 reduced the glycosylation of the P-glycoprotein and decreased its membrane localization, thereby sensitizing cancer cells to docetaxel." (PMID 25181275, 2014). "Taken together, our results support the possibility that glycosylated CD63 by RPN2 plays an important role in cancer malignancy through the regulation of protein localization." (PMID 24884960, 2014). "RPN2 is speculated to be involved in the progression of malignant tumours by regulating various signalling pathways, such as STAT3, NF-κB, and PI3K-Akt." (PMID 36291587, 2022). "The abnormally high expression of RPN2 in a variety of cancer subtypes plays an important role in the drug resistance and invasion progression of cancer cells by regulating the N-terminal glycosylation of various proteins such as p-glycoprotein, CD63, and epidermal growth factor receptor (EGFR)." (PMID 35265520, 2022). "There was a significant positive correlation between RPN2 and these cancer-promoting pathways." (PMID 36168628, 2022). "In addition, the cancer-promoting signaling pathways were significantly upregulated in RPN2-high GBM samples compared with RPN2-low GBM samples, as estimated via the GSVA algorithm." (PMID 36168628, 2022). "Chemoresistance is another main factor resulting in the poor prognosis of LSCC patients, and RPN2 has been verified to be related to chemoresistance in many cancers; hence, it is of great value to further investigate the relationship between RPN2 and chemoresistance in LSCC." (PMID 35156537, 2022). "Elevated RPN2 levels have been documented to exhibit oncogenic functions in various cancers." (PMID 33613755, 2021). "RPN2 is multifunctional; it has been demonstrated to be a prognostic marker of many cancers." (PMID 33692975, 2021). "However, little is known about the correlation between ribophorin II expression and the response of oral squamous carcinoma cells to capsaicin, a natural compound with chemopreventive effect in a variety of cancers." (PMID 34512323, 2021). "It was proven that the amount of RPN2 gene product is related to drug-resistance in tumor cells, which indicates that RPN2 might be a candidate marker to predict cancer." (PMID 34575229, 2021). "We conducted a bioinformatic analysis of RPN2 expression using the UCSC Cancer Genomics Browser and GEPIA database and performed an immunohistochemical assessment of RPN2 expression in biopsy specimens from 34 GBM patients who had received radiation-based therapy." (PMID 32404045, 2020). "In addition to the wnt/β-catenin signaling pathway, numerous studies have proven that RPN2 promotes cancer progression by regulating various signaling pathways." (PMID 33087705, 2020). "Moreover, shRNAs-triggered RPN2 silencing has been shown to suppress lung tumor formation and increase cancer cell sensitivity to cisplatin." (PMID 32404045, 2020). "RPN2 exerts tumor genetic functions in many kinds of cancer." (PMID 30940778, 2019). "Recently, it was also reported that RPN2 expression may be a potential therapeutic target for drug resistance and a promising prognostic biomarker for various types of cancer." (PMID 25595901, 2015). "RPN2 has also been revealed to contribute to the resistance of tumor cells to chemotherapeutic agents, including docetaxel and taxane, in animal models of breast and ovarian cancers, and in clinical studies of breast and esophageal squamous cell carcinoma." (PMID 25789057, 2015).
cancer (continued). "We also investigated whether RPN2 affects cancer malignancy in vitro and tumor growth and drug resistance in vivo." (PMID 25595901, 2015). "Collectively, the RPN2 gene may represent a novel target for RNAi therapeutics against a wide range of malignant neoplasms." (PMID 25181275, 2014). "These phenotypes were similar to those observed in RPN2-mediated cancer malignancy." (PMID 24884960, 2014). "We previously showed that RPN2 contributes to invasiveness and drug resistance in cancer cells." (PMID 24884960, 2014). "However, prior to developing an anti RPN2 therapy against cancer stem cells, the safety of the effect of RPN2 silencing in normal tissue stem cells should be tested." (PMID 24212663, 2011). "Interestingly, CALU, directly interacting with DDOST and RPN2, is known to be highly expressed in tumor cells and therefore might play a crucial role in cancer progression and the induction of epithelial-to-mesenchymal transition." (PMID 39223141, 2024). "Consequently, this evidence suggests that RPN2 may act as a significant oncogene and be involved in cancer progression and treatment resistance by activating a variety of carcinogenic signaling pathways." (PMID 33087705, 2020). "Moreover, various studies have shown that cancer cell proliferation is inhibited by RPN2 silencing." (PMID 29069815, 2017). "Additionally, we also investigated whether RPN2 affected cancer malignancy in vitro as well as tumor growth and drug resistance in vivo." (PMID 25595901, 2015). "Therefore, the localization of CD63, which is regulated by RPN2, might contribute to cancer malignancy." (PMID 24884960, 2014). "We observed that four subunits of OST showed a coordinated reduction in the inclusion of TRD from pre- to post-natal stages, which increased again in cancer patients in brain, with TUSC3 and RPN2 undergoing greatest change." (PMID 36509773, 2022). "To further validate our bioinformatic approach we selected two other circRNAs deregulated in cancer, SMG7 and RPN2." (PMID 29262850, 2017). "We found that RPN2 silencing reduced glycosylation of EGFR, a highly N-link glycosylated cell surface glycoprotein that plays a critical role in majority of human cancers correlating with increased cell growth, proliferation, and differentiation." (PMID 29069815, 2017). "Based on this strong evidence supporting these novel functions of RPN2, we suggest that RPN2 expression not only controls DTX sensitivity but also plays multifunctional roles in various types of cancer cells." (PMID 25595901, 2015). "In conclusion, this study provides evidence of a novel and important function of RPN2-mediated glycosylation of CD63 in the regulation of MDR1 localization and cancer malignancy, including drug resistance and invasiveness." (PMID 24884960, 2014). "To further confirm the relationship between RPN2 and MCL1, we analyzed MCL1 expression in the Cancer Genome Atlas (TCGA) database, and found that MCL1 expression was also higher in GBM primary tumors, and positively correlated with the expression of RPN2." (PMID 32404045, 2020). "Previous study indicated that RPN2 expression predicted response to docetaxel in oesophageal squamous cell carcinoma, while few studies reported the biological role of Ribophorin I (RPN1) in the occurrence and progression of cancers." (PMID 30940778, 2019). "Moreover, RPN2 silencing reduced the glycosylation of MDR1 and decreased its membrane localization, which thereby sensitized the cancer cells to DTX." (PMID 25595901, 2015). "In addition, silencing of RPN2 reduced the glycosylation of MDR1 and decreased its membrane localization, thereby sensitizing cancer cells to docetaxel." (PMID 24884960, 2014). "However, some studies have revealed that RPN2 plays a critical role in different cancers, while there was almost no study reporting the effect of RPN1." (PMID 34778038, 2021). "RPN2 overexpression has been reported to have a negative effect in several human cancers." (PMID 34575229, 2021).
tumor (27 papers, 2014 to 2025). "RPN2 silencing caused reduced glycosylation of the P-glycoprotein in vitro and markedly reduced tumor growth in vivo." (PMID 33287297, 2020). "We observed that only RPN2 expression was significantly associated with tumor stage, histological differentiation and distant metastasis." (PMID 26388988, 2015). "A total of 29.5 % of stage I/II and 51.4 % of stage III/IV specimens were positive for cytoplasmic RPN2, with a significant association between tumor stages (p = 0.047)." (PMID 26388988, 2015). "In various human malignancies, silencing of RPN2 was associated with increased apoptosis, reduced tumor growth and increased sensitivity of tumor cells to docetaxel response." (PMID 26388988, 2015). "All 30 DEPs were significantly correlated with DDOST in 179 PAAD tumor tissue samples, among which 22 were strong correlations, including RPN2, SERBP1, CALU, STT3B, YWHAZ and MAPK1." (PMID 39223141, 2024). "In xenografted mice, silencing RPN2 expression reduced tumor growth, ROS production, and levels of Ki-67, Vimentin, LDHA, and p-Akt/Akt, but enhanced E-cadherin expression." (PMID 35156537, 2022). "The influence and mechanism of RPN2 in LSCC were further verified in an established xenograft tumor model using TU212 cells stably silencing RPN2 or control." (PMID 35156537, 2022). "RPN2 mRNA expression in 25 LSCC tissues was higher than that in adjacent non-tumor specimens, which was detected by qRT-PCR." (PMID 35156537, 2022). "In the current study, we found that RPN2 was highly expressed in LSCC tissues than that in adjacent non-tumor samples." (PMID 35156537, 2022). "Increasing evidence indicates that ribophorin II is also multifunctional, in that it tightly regulates tumor initiation and malignancy." (PMID 34512323, 2021). "Silencing of ribophorin II reduces the N-linked glycosylation and membrane localization of P-glycoprotein, and in vivo delivery of ribophorin II siRNA inhibited tumor growth in mice given docetaxel." (PMID 34512323, 2021). "The expression of EPHB2, IL-13, MAP2, RPN2, and TRAF5 was correlated with microsatellite instability (MSI), while the expression of IL-13, RPN2, and TRAF5 was related to tumor mutation burden (TMB)." (PMID 33937013, 2021). "Knockdown of RPN2 inhibited tumor proliferation and invasion, promoted apoptosis, and enhanced temozolomide (TMZ) sensitivity in vitro and in vivo." (PMID 33087705, 2020). "The expression of RPN2 was also higher in GBM patients with tumor recurrence, who were classified to be resistant to radiation therapy." (PMID 32404045, 2020). "In summary, these data indicate that the silencing of RPN2 can significantly repress tumor growth and sensitize tumors to TMZ in vivo, which was consistent with the in vitro assay results." (PMID 33087705, 2020). "TCGA RNA-Seq data showed a marked upregulation of RPN2 in GBM tumor tissues compared to normal control tissues." (PMID 32404045, 2020). "We found that the patients with tumor recurrence had higher RPN2 expression at the mRNA and protein level." (PMID 32404045, 2020). "The tumor-suppressive effect of silencing RPN2 was also studied using in vivo xenograft experiments." (PMID 30940778, 2019). "Down-regulation of RPN2 expression also inhibited tumor growth in vivo, and dramatically reduced tumor size and weight in a xeno-transplanted tumor model." (PMID 30940778, 2019). "In the xenograft tumor model study, we found that tumor volume and weight in mice inoculated with RPN2- or EGFR-silenced CRC cells were significantly decreased compared with control mice." (PMID 29069815, 2017). "We also found that the expression of EGFR in CRC tissues was positively correlated with the expression level of RPN2 and tumor size." (PMID 29069815, 2017). "We found that RPN2 protein levels were markedly upregulated in primary CRC tissues compared with adjacent non-tumor tissues." (PMID 29069815, 2017). "We observed an increase in RPN2 expression in the tumor tissue compared with normal tissues (P = 0.0019)." (PMID 25595901, 2015).
tumor (continued). "Here, we examined RPN2 expression in tumor specimens from recurrent NSCLC patients after resection (n = 32 and = 177) and assessed the correlation between RPN2 expression and various clinical features." (PMID 25595901, 2015). "Over-expression of RPN2 in stage II CRC was also reported by another microarray that focused on CRC tumor metastasis, supporting its implication beyond early staged tumors." (PMID 26388988, 2015). "In the present study, we show that the RPN2 gene is significantly correlated with early and distant tumor recurrence as well as poor survival in NSCLC patients." (PMID 25595901, 2015). "To examine the role of RPN2 in primary tumor growth and metastasis, we transplanted 143B-shRPN2 and 143B-shNC cells into mice and evaluated the resulting tumor progression." (PMID 25181275, 2014). "In this study, we found that RPN2 silencing contributed to inhibition of tumor growth and lung metastasis formation in vivo." (PMID 25181275, 2014). "For this reason, we were unable to draw any clear conclusions about the correlation between RPN2 expression in biopsy samples and tumor response to neoadjuvant chemotherapy, while most patients in the high-RPN2 group were poor responders." (PMID 25181275, 2014). "Moreover, similar to GSVA enrichment analysis, the GSEA results also showed that classical pathways involved in tumor pathogenesis were significantly enriched in the high RPN2 expression group in the TCGA GBM dataset." (PMID 36168628, 2022). "Furthermore, the in vivo delivery of ribophorin II siRNA inhibits tumor growth in mice given docetaxel." (PMID 34512323, 2021). "In a word, these results implied that higher expression of most OST members, especially RPN1 and RPN2, were significantly correlated with poor prognostic outcome and might play a pro-tumor function." (PMID 34778038, 2021). "Additionally, TMZ treatment (TMZ group) retarded tumor growth compared with the NC group, and the group with treatment in combination with shRPN2 and TMZ (sh-RPN2 + TMZ) showed the smallest tumor volume in comparison to the other groups." (PMID 33087705, 2020). "However, our data uncovered the vital role of the RPN2/wnt/β-catenin axis in miR-181c mediated tumor suppression and TMZ sensitivity." (PMID 33087705, 2020). "Moreover, the tumor tissues were collected and the levels of circNFIX, miR-378e and RPN2 were detected." (PMID 31888753, 2019). "Down-regulation of RPN2 significantly delayed tumor growth in vivo (P<0.001)." (PMID 30940778, 2019). "RPN2 over-expression could promote cell viability, migration, and invasion of many kinds of tumor cells." (PMID 30940778, 2019). "Moreover, clinicopathological analysis revealed that RPN2 expression level was strongly correlated with several variables including disease stage, differentiation, and tumor size." (PMID 29069815, 2017). "However, tumor volume and weight were smaller in mice with RPN2-silenced than in EGFR-silenced mice." (PMID 29069815, 2017). "In this study, we examined RPN2 expression in tumor specimens from NSCLC patients who experienced recurrence after curative resection and assessed the correlation between RPN2 expression and the clinical features such as recurrence phenotypes and overall survival." (PMID 25595901, 2015). "Further studies are needed to elucidate whether the glycosylation status of CD63 plays a role in tumor cell invasion and metastatic phenotypes regulated by RPN2 in NSCLC." (PMID 25595901, 2015). "In this animal model of orthotopically implanted, docetaxel-resistant breast tumors, it was revealed that RPN2 silencing effectively facilitated the accumulation of docetaxel in tumor cells, augmented docetaxel-induced apoptotic cell death, and suppressed tumor growth." (PMID 25789057, 2015). "Furthermore, RPN2 knockdown dramatically reduced the tumor size and weight (P<0.001)." (PMID 30940778, 2019).